LAG3 (lymphocyte activating 3)
Diseases named in the same sentence as LAG3 in open-access papers (continued):
Sharing a sentence is not in itself a finding about the gene and the disease.
leukemia (continued). "With targeted RNA-sequencing, we found upregulation of immune exhaustion genes in T-cells, including Lag3, Tigit, and Il10, in mice with leukemia compared to those without." (PMID 35831470, 2022). "Staining for exhaustion markers LAG3 and TIGIT demonstrated an increase in expression on CD3+ T-cells in vehicle treated mice with leukemia between days 7 and 11, which is diminished by treatment with IL-12, generally consistent with the gene expression analyses." (PMID 35831470, 2022). "Despite these observations, treatment with anti-PD-1 and anti-LAG-3 antibodies failed to enhance the survival of leukemia-bearing mice transferred with TCRTg101 and did little to reverse the dysfunctional TCRTg101 phenotype." (PMID 34758311, 2021). "Of interest, CD4+ T cells from spleens of leukemia-bearing Rag2−/− mice showed a higher frequency of TR1 cells in comparison to non-leukemic control mice, accompanied by a high co-expression of LAG3 on these cells." (PMID 33526861, 2021). "Expression of exhaustion markers PD-1, LAG-3 and TIM-3 on T cells could be further upregulated in leukemia patients after addition of Blinatumomab." (PMID 27708227, 2016). "In addition, we detected increased expression of PD-L1 on the NFKBIE-ko leukemia cells as well as increased expression of PD-1, TIGIT and LAG3 on CD4+ and CD8+ T-cells from the spleens of mice with NFKBIE-ko tumors, consistent with the exhausted phenotype predicted by the RNAseq analysis." (PMID 38486128, 2024). "Interestingly, the Tregs A subpopulation is positive for already reported markers of CLL-related Tregs, including IL-10, LAG-3, granzyme B, EOMES, as well as share a unique gene expression signature of chemokines that may support leukemia progression and formation of leukemic microenvironment." (PMID 35296093, 2022). "T cells from leukemia-bearing mice presented increased expression of inhibitory co-receptors including programmed cell death protein 1 (PD1), Tim3 and LAG3, and introduction of a CAR into these T cells failed to fully reverse poor in vivo function." (PMID 30791947, 2019).
renal cell carcinoma (27 papers, 2017 to 2025). "We confirmed that LAG3 promotes the progression and metastasis of renal cell carcinoma and is positively correlated with CD8+ T cells using cell phenotype studies and immunohistochemistry." (PMID 38291496, 2024). "The increased expression of LAG-3 and PD-1 in TILs has been established on renal cell carcinoma (RCC)." (PMID 36140182, 2022). "They evaluated LAG-3 expression in renal cell carcinoma (RCC) cells, and high LAG-3+ RCC was correlated with an elevated level of tumor-infiltrating immune cells." (PMID 37007114, 2023). "It has been reported that high expression profiling of the inhibitory receptors LAG-3, TIM-3, and TIGIT in renal cell carcinoma refers to malignancy and decreased survival." (PMID 36829161, 2023). "who reported an increase of LAG-3+ and TIM-3+ CD4+ and CD8+ T cells in an in-vitro PD-1 ICB assay in renal cell carcinoma TILs." (PMID 35874702, 2022). "By applying an automated single-cell count for immunolabelled LAG-3, TIM-3, and TIGIT, we reveal that individual IR levels with exclusive domination in each tumour can serve as valid biomarkers for profiling human renal cell carcinoma (RCC)." (PMID 34545095, 2021). "A similar phenotype is observed in CD8+TILs from patients with renal cell carcinoma (RCC), colorectal cancer (CRC), and NSCLC that display upregulation of PD-1, TIGIT, Lag-3, and Tim-3 with reduced CD226 expression." (PMID 33670993, 2021).
metastatic disease (24 papers, 2018 to 2025). "In studies on NSCLC, low levels of s-LAG3 were reported to be associated with locally advanced or metastatic disease spread." (PMID 38668032, 2024). "Lastly, using logistic regression, we confirmed that an increasing percent of exhausted PD1+LAG3+CD8+ T cells was associated with increased odds of progression to metastatic disease (OR 1.39, 95% CI 1.02–1.90, p = 0.038)." (PMID 38339231, 2024). "A recent meta-analysis on the prognostic value of LAG3 in cancer proposed LAG3 expression to be associated with better overall survival, with a trend towards higher benefit in early stage cancer than in metastatic disease." (PMID 32861198, 2020). "The trend toward an association of LAG3 expression with outcome was higher in early stage cancer than in metastatic disease." (PMID 32861198, 2020). "In NSCLC, low serum LAG-3 expression was associated with advanced or metastatic disease." (PMID 34691076, 2021). "This challenges the notion that these tumors are “cold, immune deserts” and is consistent with recent publications of single-cell sequencing of metastatic tumors, demonstrating that checkpoints such as LAG-3 are present in the majority of these tumors." (PMID 35681616, 2022). "Especially the use of anti-PD-L1 and anti-LAG-3 in combination with AU-011 may enhance the therapeutic outcome in patients with both primary and metastatic tumors." (PMID 36997666, 2023). "Moreover, while the advanced metastatic disease is targeted, PD-1 and LAG-3 expression within distant metastatic breast cancer remains understudied." (PMID 33413541, 2021). "In advanced metastatic disease, second-generation immune checkpoint inhibitors (e.g., TIGIT, LAG3, TIM3) added to an ICI and anti-VEGF backbone suggests the future of first-line HCC treatment is moving towards triplet systemic therapy." (PMID 39858016, 2025). "In this study, we assessed LAG3 protein levels in leukocytes in normal kidney adjacent to RCC, primary RCC tumors, and matched metastatic tumors, including large numbers of brain metastases." (PMID 36313654, 2022).
lung adenocarcinoma (23 papers, 2019 to 2025). A carcinoma that arises from the lung and is characterized by the presence of malignant glandular epithelial cells. "Regarding targetable molecule expressions, lung adenocarcinomas were characterized by high PD-L1, but mesothelioma by high LAG-3." (PMID 31817531, 2019). "Finally, we found that COL11A1 is positively correlated with HAVCR2(TIM3), CD274 (PD-L1), CTLA4, and LAG3 in lung adenocarcinoma." (PMID 38649961, 2024). "Moreover, the SUMO-C1 group showed a higher expression of co-stimulatory and MHC molecules and lower expression of co-inhibitory molecules, such as CD274, PDCD1, and LAG3, which are now commonly used as immunotherapeutic checkpoints in lung adenocarcinoma." (PMID 37123398, 2023). "Interestingly, the LAG-3 gene is higher expressed on mesothelioma tumors compared to lung adenocarcinoma, while PD-L1 gene is higher expressed is lung adenocarcinoma." (PMID 34249695, 2021). "Indeed, lymphocyte activation gene 3 (LAG3), T-cell immunoreceptor with Ig and ITIM domains (TIGIT), and T-cell immunoglobulin and mucin domain 3 (TIM3) are linked to resistance and clonal selection in lung adenocarcinoma." (PMID 40573308, 2025). "Therefore, we aimed to conduct a comprehensive analysis of the co-expression patterns of PD1, LAG3, TIGIT, and TIM3, their prognostic significance, and their association with tumor transcriptomics in patients with advanced lung adenocarcinoma undergoing treatment with PD1/PD-L1 inhibitors." (PMID 39591972, 2024). "Then, multivariate ROC showed that programmed cell death risk score (AUC:0.705) was more effective than PD-1 (AUC:0.453), PD-L1(AUC:0.497), CTLA4(AUC:0.417), TMB(AUC:0.506), LAG3(AUC:0.485), TIM-3(AUC:0.419), and MSI(AUC:0.475) in predicting the prognosis of lung adenocarcinoma." (PMID 36983658, 2023). "Briefly, this human A549 lung adenocarcinoma derived line expresses a membrane-bound anti-CD3 single-chain antibody (A549-SC3 cells) for T cell engagement and both MHC-II and PD-L1 which can provide inhibitory interactions through LAG3 and PD1 respectively on the T cells." (PMID 34969998, 2022).
Hodgkins lymphoma (22 papers, 2018 to 2025). A heterogeneous group of malignant lymphoid neoplasms of B-cell origin characterized histologically by the presence of Hodgkin and Reed-Sternberg (HRS) cells in the vast majority of cases. "A new Hodgkin lymphoma-associated T-cell subset with prominent suppressant receptor LAG3 expression was recognized by single-cell expression profiling, and this LAG3+ T-cell population-mediated immunosuppression was ascertained by functional analysis." (PMID 39552788, 2025). "For instance, the higher expression of LAG-3 and tumor-associated macrophages (TAMs) significantly increased in patients with Hodgkin’s lymphoma and were associated with shorter PFS and OS." (PMID 39660130, 2024). "LAG-3 is an immune checkpoint thought to be associated with immunological tumor escape in several types of solid tumors as well as in Hodgkin lymphoma." (PMID 34771650, 2021). "LAG-3 inhibits the antitumoral effect of anti-PD-1 and anti-LAG-3 therapy in Hodgkin lymphoma by inhibiting the CD4+ T-cell response." (PMID 37484526, 2023). "In a study of Hodgkin’s lymphoma, EBV infection increased gene expression of LAG3 and immunosuppressive cytokines associated with type-1 T regulatory cells (Tr1)." (PMID 37311986, 2023). "In this regard, anti-LAG-3 therapy is in phase I trials and based on encouraging preclinical results in MHC II expressing tumors, such as Hodgkin’s Lymphoma; anti-LAG3 therapy in combination with anti-PD1 is also under clinical investigation." (PMID 33562694, 2021). "LAG-3 was found expressed on a majority of tumor infiltrating lymphocytes in pediatric Hodgkin lymphoma, and there was a positive relationship between the presence of LAG-3 and PD-L1 expression." (PMID 34771650, 2021). "The second finding in our study was an overexpression of LAG-3 on the CD4+ lymphocyte surfaces of the microenvironment of Hodgkin lymphoma, in patients exposed to anti-PD-1 immunotherapy." (PMID 34771650, 2021). "The combination of anti-PD-1 and anti-LAG3 therapy, which regulates the populations of T cells, may be beneficial in Hodgkin lymphoma (HL)." (PMID 35111155, 2021). "In tumor tissues, regulatory T cells (Tregs) undergo abnormal changes in expression, such as the change in LAG3 expression observed in classic Hodgkin lymphoma, upregulated LAYN expression in FOXP3 + Helios + Tregs, and changes in CCR8 and IL1R2 expression in HCC." (PMID 34108022, 2021). "The combination of anti-PD-1 and anti-LAG-3 therapy may be beneficial in Hodgkin lymphoma (HL)." (PMID 36077354, 2022). "Similar observations were made in patients with Hodgkin lymphoma and non-Hodgkin lymphoma, where CD4 + and CD8 + T lymphocytes in the peripheral blood expressed elevated levels of LAG-3." (PMID 39425148, 2024). "The main results show that immunotherapy-resistant Hodgkin lymphoma had CD8 lymphocytes depleted in microenvironment and overexpression of the LAG-3 molecule." (PMID 34771650, 2021). "Hodgkin lymphoma exposed to anti-PD-1 correlated in tumor microenvironment with an immune depletion of CD8+ T lymphocytes and overexpression of LAG-3 on CD4+ helper T lymphocytes." (PMID 34771650, 2021). "LAG 3 and BTLA4 have been involved in the immunosuppression in Hodgkin lymphoma and synergistic effects in the restitution of the exhausted immune response between anti-PD1 and anti-LAG3 have been shown in several tumor systems." (PMID 29755699, 2018). "Our study suggests that anti-PD-1 immunotherapy-resistant Hodgkin lymphoma could correlate in tumor microenvironment with an immune depletion of CD8+ T lymphocytes and overexpression of LAG-3 on CD4+ helper T lymphocytes." (PMID 34771650, 2021). "However, there are many studies that could not find a significant association between LAG3 expression and any of the clinical features in NSCLC, CRC, and Hodgkin lymphoma." (PMID 36765348, 2023).
pancreatic cancer (22 papers, 2020 to 2025). "LAG-3, is one of suppressive immune checkpoints expressed on the surface of T cells, which has been reported to be associated with reduced survival in pancreatic cancer." (PMID 37256126, 2023). "LAG-3-expressing tumor-infiltrating T-cells were associated with a worse chance of progression-free survival in patients with pancreatic cancer." (PMID 36359832, 2022). "Multiple clinical trials have shown that LAG-3 blockade alleviates resistance to PD-1 inhibitors in pancreatic cancer." (PMID 37305389, 2023). "In pancreatic cancer high LAG-3 expression on tumor-infiltrating lymphocytes is strongly connected with PD-1 and CTLA-4 expression." (PMID 36077354, 2022). "Recent studies have shown that the combination of T cell checkpoint 41BB agonist and LAG3 antagonist could improve the anti-tumor immunity in pancreatic cancer." (PMID 38115039, 2023). "As such, in pancreatic cancer, CAFs have been reported to increase the expression of PD-1, cytotoxic lymphocyte-associated antigen-4 (CTLA-4), lymphocyte-activation gene-3 (LAG-3), and T cell immunoglobulin and mucin-domain containing-3 (TIM-3), on both CD4+ and CD8+ T cell." (PMID 36338519, 2022). "LAG-3+ T cells may not only represent a novel prognostic marker, but may also be a particularly attractive target for immunotherapeutic strategies in patients with pancreatic cancer." (PMID 33803936, 2021). "To determine the expression profile of co-stimulatory and inhibitory T cell receptors in the pancreatic tumor microenvironment, we performed multiplex immunofluorescence for CD3, ICOS, LAG-3, PD-1, VISTA, and pan-cytokeratin (PanCK)." (PMID 33803936, 2021). "To predict the pancreatic cancer patients’ response to immunotherapy, we further investigated the difference in the expression of immune checkpoints (PD-1, PD-L1, CTLA-4, LAG3, TIGIT and TIM-3) between patients with low and high m6Ascore." (PMID 34332578, 2021). "We also examined PD-1, Tim-3, and LAG-3 by flow cytometry, finding a significant reduction in surface levels of these T cell exhaustion markers in mifepristone-treated HY24409 pancreatic tumors." (PMID 34873175, 2021).
chronic lymphocytic leukemia (21 papers, 2018 to 2025). "Relatlimab, the first LAG-3 mAb, has shown promising anti-tumor effects in chronic lymphocytic leukemia (CLL) by restoring the immune activities of NK cells and T cells." (PMID 39660130, 2024). "Lino and colleagues showed that LAG-3 is highly expressed in patients with chronic lymphocytic leukemia (CLL), a lymphoid neoplasm characterized by clonal expansion of mature B cells." (PMID 37509517, 2023). "LAG3 and PD-1 were previously shown to be co-expressed in chronic lymphocytic leukemia antigen-specific CD8 + T cells, contributing to the dysfunctionality of CD8 + T cells." (PMID 37149620, 2023). "In chronic lymphocytic leukemia, LAG-3 also serves as a new predictive marker: higher expression of LAG-3 was associated with shorter survival." (PMID 34454491, 2021). "High expression of LAG-3 has also been shown in chronic lymphocytic leukemia cells (CLL), characterized by clonal expansion of mature B-cells (CD5+ CD23+ CD27+ Iglow)." (PMID 34067904, 2021). "This is in line with data published for chronic lymphocytic leukemia, where PD-1 blockade abolished the positive effect induced by anti-LAG-3 antibodies in combination with CD3/CD28 beads as a very strong stimulus." (PMID 29535740, 2018). "Higher expression of LAG3 and PD-1 in CAR T-cells products predicted impaired in vivo expansion, subsequently poor therapeutic responses in the chronic lymphocyte leukemia." (PMID 36932256, 2023). "Murine models of chronic lymphocytic leukemia (CLL) treated with both anti-PD-1 and anti-LAG3 displayed a significantly lower number of CLL cells in the spleen, along with a decrease in Tregs and an increase in Teffs." (PMID 35345849, 2022). "Chronic lymphocytic leukemia (CLL) B cells and tumor microenvironment (TME) bystander cells incite a tolerogenic environment through soluble factors (e.g., IL-10) and immune inhibitory molecules (e.g., PD-L1, LAG3)." (PMID 38775157, 2024). "Also, patients with chronic lymphocytic leukemia (CLL) exhibit an upregulation of LAG-3 on leukemic blasts, NK cells and T lymphocytes, accompanied by high amounts of soluble LAG-3 (sLAG-3) in plasma, that correlated with impaired outcome." (PMID 34394116, 2021). "Therefore, LAG-3 was found to be expressed both on T and malignant B cells in diffuse large B cell lymphoma (DLBCL) and chronic lymphocytic leukemia (CLL), especially in Richter transformation (RT), and had a negative impact on progression-free survival (PFS) and overall survival (OS) in DLBC." (PMID 38203720, 2023).